KCNJ14 (potassium inwardly rectifying channel subfamily J member 14)
Description:
Inward rectifier potassium channels are characterized by a greater tendency to allow potassium to flow into the cell rather than out of it. Their voltage dependence is regulated by the concentration of extracellular potassium; as external potassium is raised, the voltage range of the channel opening shifts to more positive voltages.
Synonyms: IRK4; Kir2.4
Tractability: Small molecule: it belongs to a druggable protein family. Antibody: its Gene Ontology location is reachable by antibodies, with high confidence; UniProt predicts a signal peptide or a membrane-spanning region.
Gene: Protein-coding gene on chromosome 19 (48,455,574 to 48,466,980, forward strand). Ensembl gene ENSG00000182324.
Subcellular location: Membrane
Pathways (Reactome):
Muscle contraction: Phase 4 - resting membrane potential
Neuronal System: Classical Kir channels
Gene Ontology:
Molecular function: inward rectifier potassium channel activity
Biological process: potassium ion import across plasma membrane; potassium ion transport
Cellular component: plasma membrane; voltage-gated potassium channel complex; membrane
Genetic constraint (gnomAD): Loss-of-function variants: 20 observed, 21.16 expected, observed/expected ratio (o/e) 0.95, 90% interval 0.66 to 1.37. The upper end of that interval is the gene's LOEUF score, 1.37, which puts it in group 5 of 6, group 1 being the genes least tolerant of losing a copy. Missense variants: 633 observed, 575.23 expected, observed/expected ratio (o/e) 1.1, 90% interval 1.03 to 1.17. Synonymous variants: 288 observed, 242.56 expected, observed/expected ratio (o/e) 1.19, 90% interval 1.08 to 1.31.
Homologues: Orthologues: chimpanzee KCNJ14 (99% identical), macaque KCNJ14 (99% identical), rabbit KCNJ14 (96% identical), dog KCNJ14 (94% identical), guinea pig KCNJ14 (94% identical), pig KCNJ14 (94% identical), mouse Kcnj14 (94% identical), rat Kcnj14 (94% identical), tropical clawed frog kcnj14 (64% identical), zebrafish kcnj14 (60% identical). Paralogues in human: KCNJ2 (58% identical), KCNJ12 (56% identical), KCNJ18 (56% identical), KCNJ4 (55% identical), KCNJ9 (43% identical), KCNJ3 (41% identical), KCNJ5 (41% identical), KCNJ6 (40% identical), KCNJ11 (37% identical), KCNJ16 (36% identical), KCNJ8 (35% identical), KCNJ1 (33% identical), and 3 more.
Diseases named in the same sentence as KCNJ14 in open-access papers:
KCNJ14 is named in the same sentence as 12 diseases in open-access papers, as found by Europe PMC text mining. Sharing a sentence is not in itself a finding about the gene and the disease. The quoted sentences say what the papers report.
colorectal cancer (2 papers, 2022 to 2025). A primary or metastatic malignant neoplasm that affects the colon or rectum. "Collectively, these results suggest that high KCNJ14 expression is an independent risk factor for the prognosis of patients and may play a pathogenic role in colorectal cancer." (PMID 36100894, 2022). "In this study, we demonstrated that high KCNJ14 expression is positively correlated with tumour stage, suggesting that KCNJ14 may be a pathogenic gene in colorectal cancer; therefore, we further verified the effect of KCNJ14 expression on the cellular behaviour of colorectal cancer cells." (PMID 36100894, 2022). "This indicates that KCNJ14 regulates the activity of the mTOR signalling pathway in the pathological process of colorectal cancer." (PMID 36100894, 2022). "To further verify the effect of KCNJ14 on the biological behaviour of colorectal cancer cells, we used gene interference technology to reduce the protein and mRNA levels of KCNJ14 in two colorectal cancer cell lines." (PMID 36100894, 2022). "This study is the first to report the prognostic role of high expression of KCNJ14 in colorectal cancer." (PMID 36100894, 2022). "Based on the abnormally high expression of KCNJ14 in colorectal cancer, we further explored its influence on patient prognosis." (PMID 36100894, 2022). "We further verified the adverse effects of KCNJ14 expression on the prognosis of patients with colorectal cancer." (PMID 36100894, 2022). "To determine why the expression of KCNJ14 is abnormally increased in colorectal cancer cells, we downloaded the DNA methylation data of patients with colorectal disease from the TCGA database." (PMID 36100894, 2022). "Collectively, these results suggest that knockdown of KCNJ14 expression can significantly inhibit the malignant behaviour of cancer cells in the pathological process of colorectal cancer." (PMID 36100894, 2022). "This study not only increases the molecular understanding of KCNJ14 but also provides a potentially valuable biological target for the treatment of colorectal cancer." (PMID 36100894, 2022). "KEGG analysis also showed that KCNJ14 participates in cancer-related signalling pathways in colorectal cancer, such as the mTOR, NOD-like receptor, and VEGF signalling pathways." (PMID 36100894, 2022). "Taken together, our study is the first to demonstrate that the cg17660703 high methylation status of KCNJ14 CpG sites, along with KCNJ14 expression, can be a clear indicator of poor prognosis of colorectal cancer patients." (PMID 36100894, 2022). "More importantly, the expression of KCNJ14 increased with an increase in tumour stage (P = 0.040), and the increase in tumour stage of patients with colorectal cancer was a poor prognostic factor." (PMID 36100894, 2022). "We found that the expression of KCNJ14 was much higher in colorectal cancer tissues than in adjacent tissues." (PMID 36100894, 2022). "Based on these results, the high expression of KCNJ14 in colorectal cancer may be positively regulated by the methylation site of cg17660703." (PMID 36100894, 2022). "However, only few studies have explored on the regulatory effect of KCNJ14 on the pathological process of malignant tumours, especially in the prognosis of patients with colorectal cancer." (PMID 36100894, 2022). "This study attempted to verify the potential of KCNJ14 as a biomarker in colorectal cancer (CRC)." (PMID 36100894, 2022). "To explore the difference in KCNJ14 expression in colorectal cancer tissues, we obtained colorectal cancer and adjacent tissue samples from the TCGA (cancer: 488 cases; adjacent: 42 cases) and GSE50117 (cancer: 9 cases; adjacent: 9 cases) databases, respectively." (PMID 36100894, 2022). "We next investigated whether increased KCNJ14 expression in the pathological process of colorectal cancer is regulated by DNA methylation." (PMID 36100894, 2022).
colorectal cancer (continued). "Because the pooled HR for the correlation between high KCNJ14 expression and patient OS was 2.24 (95% CI: 1.37–3.65), we can conclude that KCNJ14 high expression is an independent predictor of unfavourable OS in patients with colorectal cancer." (PMID 36100894, 2022). "Therefore, we only performed knockdown KCNJ14 experiments in two cell lines of colorectal cancer and found that the levels of mTOR signalling pathway-related proteins decreased significantly." (PMID 36100894, 2022). "In addition, this study provides novels insights for future studies aiming to investigate the complex pathological process of colorectal cancer and broadens the molecular knowledge on the role of KCNJ14 in the pathological process of cancer." (PMID 36100894, 2022). "We knocked down KCNJ14 in two colorectal cancer cell lines and using in vitro experiments, found that the proliferation and migration ability of cancer cells decreased significantly, thereby verifying the carcinogenic effect of KCNJ14 in colorectal cancer." (PMID 36100894, 2022). "Collectively, these results suggest that KCNJ14 may have an important regulatory effect on the pathological process of colorectal cancer." (PMID 36100894, 2022). "Hence, we infer that increased KCNJ14 expression in colorectal cancer can not only independently reduce the overall survival time of patients, but also enhance the malignant behaviour of colorectal cancer cells." (PMID 36100894, 2022). "Therefore, this study attempted to investigate the effect of KCNJ14 on the prognosis of patients with colorectal cancer and evaluate its regulatory relationship with the complex pathological process of colorectal cancer." (PMID 36100894, 2022). "Furthermore, we performed a meta-analysis and confirmed that high KCNJ14 expression is a critical prognostic factor for colorectal cancer." (PMID 36100894, 2022). "KCNJ14 deletion could significantly inhibit colorectal cancer cell growth and migration." (PMID 40041860, 2025). "Subsequently, we verified that KCNJ14 knockdown could significantly reduce the proliferation and migration of colorectal cancer cell lines and revealed the regulatory mechanism of KCNJ14 leading to poor prognosis in colorectal cancer." (PMID 36100894, 2022). "The expression level of KCNJ14 was positively correlated with CD4 + T cells in both COAD (colon adenocarcinoma) and READ (rectum adenocarcinoma) (P = 3.52e-06, COAD; P = 1.26e-05, READ) and negatively associated with CD8 + T cells in colorectal cancer (P = 2.18e-05, COAD; P = 1.58e-02, READ)." (PMID 36100894, 2022). "In addition, we also uploaded the genes with expression relationships with KCNJ14 to the CMap database to match the inhibitory drug discovery and found that four candidate drugs (thiostrepton, ivermectin, corticosterone, and indoprofen) may have potential value in the treatment of colorectal cancer." (PMID 36100894, 2022). "This suggests that KCNJ14 and CD4 + T cells may exert a synergistic effect to promote the formation of an inhibitory immune microenvironment in colorectal cancer." (PMID 36100894, 2022).
cancer (4 papers, 2022 to 2025). A tumor composed of atypical neoplastic, often pleomorphic cells that invade other tissues. "In this study, KCNJ14 pan-cancer analysis was conducted to explore its association with cancer progression and development." (PMID 36768373, 2023). "KCNJ14 mutations were studied by utilising the cBioPortal database for information on their prevalence, mutation location, and prognostic impact in cancer." (PMID 36768373, 2023). "Data analysis revealed that KCNJ14 mutated in 1% of 26 types of cancers, with amplification being the main kind of mutation in 12.84 % of these cases." (PMID 36768373, 2023). "Additionally, KCNJ14 was found to be associated with cancer progression as its expression increased with pathological stages." (PMID 36768373, 2023). "Potassium Inwardly Rectifying Channel Subfamily J Member 14 (KCNJ14) is one of the cancer genome’s least investigated genes, but using several databases, it has been found to be involved in cancer stemness." (PMID 40804837, 2025). "Potassium Inwardly Rectifying Channel Subfamily J Member 14 (KCNJ14) is one of the cancer genome’s least investigated genes that is involved in cell survival, RNA modification, and cancer stemness." (PMID 40804837, 2025). "KCNJ14 was shown to be dysregulated in a variety of cancers, including lung, intestinal, head and neck, oesophageal, and stomach." (PMID 36768373, 2023). "This study conducted a comprehensive examination of the relationships between KCNJ14 gene expression analysis, survival, RNA modification, immunotherapy participation, and cancer stemness using several databases." (PMID 36768373, 2023). "Potassium Inwardly Rectifying Channel Subfamily J Member 14 (KCNJ14) is one of the cancer genome’s least investigated genes." (PMID 36768373, 2023). "In this study, KCNJ14 expression was found to have a substantial positive connection with RNA-modification-related genes (m5C, m3C, and m7G) for a wide range of cancers." (PMID 36768373, 2023). "In this work, KCNJ14 expression was examined across 37 types of cancers using the TIMER.2 database and Sangerbox database." (PMID 36768373, 2023). "Although this work has explored the K+ channel role of KCNJ14 in cancer, it still has limitations with respect to its view." (PMID 36768373, 2023). "Overall, CD4 + T cells play a key role in regulating the cancer immune microenvironment, and our study demonstrated that KCNJ14 mainly regulates the infiltration of CD4 + and CD8 + cells to influence the development of CRC." (PMID 36100894, 2022). "To validate the possible molecular mechanism of KCNJ14, we probed the cancer-related functions of the most positively correlated co-expressed genes." (PMID 36100894, 2022). "However, in relation to cancer, KCNJ14 has been reported as a biomarker for colorectal cancer (CRC) only." (PMID 36768373, 2023). "In addition, KCNJ14’s role in immunotherapy was examined, as well as its involvement in cancer epigenetics and cancer stemness." (PMID 36768373, 2023). "This work identifies KCNJ14 as a possible prognostic biomarker for several cancer types." (PMID 36768373, 2023). "Based on these novel findings, KCNJ14 may be a useful independent prognostic biomarker for a range of cancers." (PMID 36768373, 2023). "Finally, Transwell assay results suggested that KCNJ14 knockdown can reduce the invasive ability of cancer cells." (PMID 36100894, 2022). "Considering its location and function, we speculate that as an ATP-sensitive inward rectifier potassium (K+) channel, KCNJ14 malfunctions in cancer-related microenvironment and consequently activates the following signalling pathways." (PMID 36100894, 2022). "Additionally, TMB and MSI were linked to KCNJ14 expression in a variety of human malignancies, which suggests that these findings may establish KCNJ14 as a robust predictive biomarker, a marker for patients’ response to immunotherapy, and a prospective target for cancer therapies." (PMID 36768373, 2023).
cancer (continued). "The results demonstrated that KCNJ14 was downregulated with cancer progression in BRCA; however, KCNJ14 showed higher expression in correlation with the pathological stages of COAD, LIHC, LUAD, ESAD, and STAD." (PMID 36768373, 2023). "Furthermore, this study found a positive relation between KCNJ14 and immunotherapy indicators, such as TMB, MSI, NEO, purity, and ploidy, in a variety of cancers." (PMID 36768373, 2023). "The fact that KCNJ14 primarily affects the infiltration of CD4+ and CD8+ cells was first reported in CRC, which is of importance because CD4+ T cells play a major role in controlling the cancer immune microenvironment." (PMID 36768373, 2023). "Although the mechanism of action of KCNJ14 in cancer has not been elucidated, the roles of homologous proteins in various cancers have been extensively reported." (PMID 36100894, 2022).
tumour (2 papers, 2022 to 2023). "KCNJ14 was linked to tumour mutation burden (TMB), microsatellite instability (MSI), neoantigen (NEO), and programmed death ligand 1 (PD-L1); all four are potential targets for immunotherapies." (PMID 36768373, 2023). "In addition, a favourable relationship between genomic-instability markers such as heterozygosity (LOH), homologous recombination deficiency (HRD), and mutant-allele tumour heterogeneity (MATH) was demonstrated with KCNJ14." (PMID 36768373, 2023). "Furthermore, KCNJ14 associated with NEO in five tumours, including a positive correlation with LUAD, KIRC, and ACC and a negative correlation with COAD and COADREAD." (PMID 36768373, 2023). "Additionally, KCNJ14 was shown to be linked to RNA and DNA stemness in 18 and 15 different tumour types, respectively." (PMID 36768373, 2023). "This demonstrates that KCNJ14 is significantly associated with the tumour immune microenvironment." (PMID 36100894, 2022). "QUANTISEQ algorithm analysis revealed 42 tumours correlated significantly with the expression of KCNJ14 of which 26 types of tumours showed a positive correlation with natural killer cells." (PMID 36768373, 2023). "In terms of checkpoints and suppressor cells, KCNJ14 showed a positive correlation with multiple types of tumours, except LGG, GMBLGG, and LUAD." (PMID 36768373, 2023). "In this analysis, KCNJ14 was found to have a significant positive connection with mDNAsi and mRNAsi in a total of 13 and 9 tumours, respectively." (PMID 36768373, 2023). "Tumour stemness was analysed in correlation with KCNJ14 using parameters such as DNAss and RNAss." (PMID 36768373, 2023). "Additionally, KCNJ14 demonstrated a correlation with inhibitory and stimulatory immune checkpoints with respect to tumours such as THYM, STES, STAD, LUSC, LAML, COADREAD, and COAD." (PMID 36768373, 2023). "Out of 38 tumours, 28 tumours were significantly correlated with KCNJ14 in the TIMER database." (PMID 36768373, 2023). "Univariate analysis showed that KCNJ14 and several clinical characteristics, such as lymphatic invasion, pathological TNM stage, and tumour stage (hazard ratio [HR] > 1; P < 0.05), are significantly related to OS." (PMID 36100894, 2022). "Activation of these pathways can lead to malignant progression of tumour cells; however, we could not verify the influence of KCNJ14 on these signalling pathways." (PMID 36100894, 2022). "In this work, a significant correlation between KCNJ14 and ploidy level was observed in seven tumours, of which five tumours demonstrated a significantly-positive correlation, such as LUAD, STES, STAD, KIRC, and CHOL, whereas two tumours showed a negative correlation, namely UVM and KICH." (PMID 36768373, 2023).
KCNJ14 also shares sentences with these, for which no sentence is quoted: acute promyelocytic leukemia (1 paper); colon adenocarcinoma (1); lung adenocarcinoma (1); ovarian serous cystadenocarcinoma (1); prostate adenocarcinoma (1); rectum adenocarcinoma (1); skin cutaneous melanoma (1); testicular germ cell tumours (1); thyroid carcinoma (1).